CCDC192 (coiled-coil domain containing 192)
Synonyms: LINC01183
Tractability: No criterion of Open Targets' tractability assessment is met for any kind of drug.
Gene: Protein-coding gene on chromosome 5 (127,703,361 to 127,941,507, forward strand). Ensembl gene ENSG00000230561.
Homologues: Orthologues: chimpanzee CCDC192 (98% identical), macaque CCDC192 (95% identical), dog CCDC192 (73% identical), mouse Ccdc192 (56% identical), guinea pig CCDC192 (55% identical).
Diseases named in the same sentence as CCDC192 in open-access papers:
CCDC192 is named in the same sentence as 1 disease in open-access papers, as found by Europe PMC text mining. Sharing a sentence is not in itself a finding about the gene and the disease.
CCDC192 shares sentences with these, for which no sentence is quoted: deafness (1 paper).